HOXA11 (homeobox A11)
Diseases named in the same sentence as HOXA11 in open-access papers (continued):
Sharing a sentence is not in itself a finding about the gene and the disease.
breast carcinoma (12 papers, 2014 to 2023). "Here, we report lncRNA HOTTIP, which is specifically amplified in a breast cancer cell line and is associated with breast cancer cell growth, cell cycle arrest, apoptosis, and migration, probably by partly mediating HOXA11 expression." (PMID 29415429, 2018). "Abnormal HOXA11 methylation has been implicated in breast cancer." (PMID 28038461, 2017). "CircATXN7 was found to be highly expressed in breast cancer, and overexpression of circATXN7 led to reduced breast cancer doxorubicin sensitivity by affecting miR-149-5p/HOXA11 signaling." (PMID 38186573, 2023). "Methylation at many gene promoters has been reported to have independent prognostic value in breast cancer including HOXA11, ESR1 and PITX2, HOXD13 CDH22 BRCA1 and RASSF1." (PMID 33461604, 2021). "In conclusion, using a combination of in vitro and in vivo approaches, our study highlights the molecular axes comprising HOTTIP and HOXA11 as key players in breast cancer progression." (PMID 29415429, 2018). "Altogether, these results further substantiate the presumptive role of HOTTIP and HOXA11 in breast cancer cell progression and add new information supporting their interdependently regulated expression." (PMID 29415429, 2018). "Thirdly, HOTTIP was revealed to be involved in breast cancer biology, at least partly, by mediating HOXA11 expression." (PMID 29415429, 2018). "By in vitro and in vivo experiments, our study indicated the role of lncRNA HOTTIP in breast cancer pathogenesis and its potential mechanism, by partly mediating its adjacent gene HOXA11." (PMID 29415429, 2018). "In this study, we analyzed the methylation status of HOXA11 in 264 paired breast cancer and normal tissue as well as in matched serum samples by MethyLight assay." (PMID 28038461, 2017). "This universal demethylation reagent re-expresses numbers of genes including HOXA11 and enhances chemosensitivity in breast cancer." (PMID 28038461, 2017). "Homeobox A11 (HOXA11) is one of the hypermethylated genes in breast cancer and its function in breast tumorigenesis remains elusive." (PMID 28038461, 2017). "Considering the dynamics of HOXA11 methylation in development, this result infers the potential role of HOXA11 in breast cancer initiation and promotion." (PMID 28038461, 2017). "HOXA11 expression was restored by 5-azadC, a demethylation reagent, in breast cancer cell lines in our experiment as well as in previous study." (PMID 28038461, 2017). "We employed methylation specific PCR (MSP) to determine the methylation status of HOXA11 in breast cancer cell lines." (PMID 28038461, 2017). "Despite the methylation patterns in cancer, the clinical significance of HOXA11 methylation and its function in breast cancer remains elusive." (PMID 28038461, 2017). "We evaluated the mRNA expression level of HOXA11 in another 30 pairs of breast cancer and normal tissues which were randomly chosen from the hospital's biobank." (PMID 28038461, 2017). "In conclusion, the hypermethylation of HOXA11 is an independent prognostic biomarker in breast cancer." (PMID 28038461, 2017). "Although it would be more convinced if we had the data of methylation status and expression level of HOXA11 from the same cohort, our results validate the clinical utility of HOXA11 as a biomarker in breast cancer." (PMID 28038461, 2017). "Our finding suggests that HOXA11 can be applied as a clinical biomarker of prognosis and is a potential tumor suppressor in breast cancer." (PMID 28038461, 2017). "In this study, we evaluated HOXA11 methylation level in paired breast cancer and normal tissues as well as in matched serum samples collected from 264 Chinese breast cancer patients." (PMID 28038461, 2017). "In order to investigate the function of HOXA11 in breast cancer, we employed cell proliferation assay and observed an inhibition effect in all analyzed cell lines." (PMID 28038461, 2017).
breast carcinoma (continued). "By accessing the TCGA breast cancer database, we discovered that patients with HOXA11 low expression have short overall survival time." (PMID 28038461, 2017). "We hypothesized that HOTTIP might regulate the biological behavior of breast cancer via regulating HOXA11." (PMID 29415429, 2018). "Consequently, using a series of in vitro and in vivo experiments, our study suggested that HOTTIP is involved in breast cancer tumorigenesis through positively regulating HOXA11." (PMID 29415429, 2018). "To gain further insight into the regulation of the HOTTIP/HOXA11 gene axis in breast cancer, we knocked down HOXA11 using shRNAs (short hairpin RNA, used for stable gene silencing) and chose shRNA #858 as the effective sequence of HOXA11 for the next experiments." (PMID 29415429, 2018). "In accordance, we observed that HOTTIP knockdown decreased the expression of several HOXA genes, particularly HOXA11 in a breast cancer-derived cell line, but in contrast to liver cancer cells and consistent with pancreatic cancer cells, HOTTIP does not regulate the expression of HOXA13." (PMID 29415429, 2018). "Further studies are warranted to discern the role of HOXA11 in breast cancer." (PMID 28038461, 2017). "Over expression of HOXA11 inhibits cell proliferation in four breast cancer cell lines." (PMID 28038461, 2017). "Based on previous studies and our results, HOXA11 is a potential tumor suppressor in breast cancer." (PMID 28038461, 2017). "Hence, HOTTIP may mediate, at least partly, HOXA11 expression involved in cell growth, migration, and apoptosis of breast cancer MCF-7 cells." (PMID 29415429, 2018). "Moreover, further rescue experiments revealed that HOXA11 overexpression could rescue the impact of HOTTIP knockdown in cell pathogenesis in breast cancer, and cell proliferation, colony formation, migration, and apoptosis rate were included." (PMID 29415429, 2018). "In breast cancer, HOXA11 has been proposed as a biomarker that could be used for early detection." (PMID 28423531, 2017). "Therefore, HOXA11 methylation is an independent prognostic factor in breast cancer." (PMID 28038461, 2017). "Thus, the down regulation of ZNF703 and SNAI1 by HOXA11 overexpression may contribute to breast cancer suppression." (PMID 28038461, 2017). "Firstly, by detecting the expression of HOXA genes, in both breast cancer MCF-7 cell line and normal mammary epithelial MCF-10A cell line, we found that both HOTTIP and HOXA11 were upregulated in MCF-7 cells in comparison with MCF-10A cells." (PMID 29415429, 2018). "In the present study, we elucidated the involvement of lncRNA HOTTIP in breast cancer pathogenesis and further uncovered a potential bidirectional regulatory loop between HOTTIP and HOXA11 in this process." (PMID 29415429, 2018). "Among the genes amplified in the focal regions were a cluster of HOX genes (HOXA7, HOXA9, HOXA10, HOXA11) on 7p15, AKT1 (14q32.33), IGF1R (15q26.3), ERBB2 and NEUROD2 (17q12), all of which have been reported in primary breast cancers." (PMID 24489661, 2014). "Thus, HOXA11 suppressed cell proliferation but not cell migration in breast cancer cells." (PMID 28038461, 2017). "By performing 3C PCR assays in MCF7 and MDA-MB-231 breast cancer cells and MCF10A normal breast cells, we confirmed that the HOXA9 and HOXA10 promoters physically interacted each other, while the HOXA11 promoter did not interact with the HOXA9 or HOXA10 promoter." (PMID 28748001, 2017).
Infertility (12 papers, 2012 to 2025). "There is every reason to believe that abnormal promoter hypermethylation of the HOXA10 and HOXA11 genes causes their functional shutdown, which in turn leads to disruption of the implantation process and eventually to infertility." (PMID 41153447, 2025). "The methylation status of HOXA10 and HOXA11 may serve as a potential diagnostic marker for evaluating and treating infertility." (PMID 41153447, 2025). "Infertility and implantation failure are associated with this inflammation and decreased expression of HOXA10 and HOXA11." (PMID 40305321, 2025). "The study aimed to evaluate the impact of CE on the expression ofHOXA10 and HOXA11 during the lateproliferative phase in the endometrium of infertile women." (PMID 38801313, 2024). "A study analyzing endometrial HOXA10 and HOXA11 levels during the WOI in infertile women with intramural UFs found significantly decreased levels of HOXA10 and HOXA11 and a slight decrease in E-cadherin compared to healthy fertile women." (PMID 34113609, 2021). "Mice with multiple combinations of mutations of either the Hox10 or Hox11 paralog groups have interesting kidney and limb abnormalities, but no described infertility phenotypes extending beyond those associated with the Hoxa10 and Hoxa11 genes." (PMID 30872674, 2019). "Of interest, while the Hoxa10 and Hoxa11 genes have defined functions in female fertility, single homozygous mutation of the paralogous Hoxc10, Hoxd10, Hoxc11 and Hoxd11 genes gave no reported infertility." (PMID 30872674, 2019). "This study found decreased levels of HOXA11 and LIF in the endometrium of infertile patients with fibroids compared to the control samples." (PMID 37108180, 2023). "Materials and Methods: Expression of HOXA11 and HOXA10 were examined prospectively during the midluteal phase in endometrium obtained from infertile women (n=12) with myoma before and three months after myomectomy." (PMID 24639724, 2013). "The expression of HOXA10 and HOXA11 duringthe proliferative phase is not significantly different between infertilewomen with endometritis and infertile women without endometritis.Translational studies with a larger number of patients should beperformed." (PMID 38801313, 2024). "The expression of HOXA10 and HOXA11 during theproliferative phase is not significantly different between infertile women withendometritis and infertile women without endometritis." (PMID 38801313, 2024).
gastric cancer (9 papers, 2014 to 2024). A primary or metastatic malignant neoplasm involving the stomach. "An increasing number of reports suggest that HOXA11 has been implicated in several malignant tumors, such as gastric cancer, renal cell carcinoma, NSCLC and lung adenocarcinoma, and breast cancer." (PMID 29914539, 2018). "For example, HOXA11-OS can increase the expression of integrin β3 through sponging the miRNA miR-124-3p, which can promote the migration and invasion of gastric cancer." (PMID 36418932, 2022). "Increasing studies have shown that HOXA11-OS has regulatory effects on genes in gastric cancer, prostate cancer, and various kidney diseases, but research on its role in systemic lupus erythematosus is still lacking." (PMID 36418932, 2022). "For example, HOXA11-OS has regulatory effects on genes in oral squamous cell carcinoma, gastric cancer, prostate cancer, and various kidney diseases." (PMID 36418932, 2022). "Collectively, the data demonstrated that HOXA11 and Stat3 form a positive-feedback loop which enhances the stemness of gastric cancer cells, subsequently resulting in promotion of migration and invasion, adhesion and resistance to apoptosis." (PMID 31695791, 2019). "Collectively, these experiments indicated that HOXA11 is the target gene of transcription factor Stat3, and both of them form a positive-feedback loop regulating the malignant phenotype of gastric cancer cells." (PMID 31695791, 2019). "Akin to stemness, the adhesive ability of gastric cancer cells induced by HOXA11 were blocked by BBI608 or knockdown of CD44s respectively (NCI-N87: BBI608: p<0.0001, shCD44s: P<0.0001; SGC-7901: BBI608: P<0.0001, shCD44s: P<0.0001)." (PMID 31695791, 2019). "Our data indicated that HOXA11 regulated adhesion, migration and invasion and anti-apoptosis of gastric cancer cells through modulating Stat3 activation can be abolished by BBI608." (PMID 31695791, 2019). "We found, using in vivo, in vitro, in silico and gastric cancer tissue studies, that HOXA11 is a potent activator of peritoneal metastasis in gastric cancer." (PMID 31695791, 2019). "Very fascinatingly, we found that upregulation of HOXA11 in gastric cancer cells resulted in increased expression of cancer stem cell factors such as CD44, CD90, CD133 and Bmi1 as well as pluripotency markers Nanog and Sox2 and vice versa." (PMID 31695791, 2019). "In our experiment, HOXA11 can be found in nucleus and positively affect the peritoneal metastasis ability of gastric cancer cells in vivo." (PMID 31695791, 2019). "In addition, the down-regulation of HOXA11 contributes to the loss of tumor suppressive function in gastric cancer (GC)." (PMID 28423531, 2017). "The results of in vivo study shown that BBI608 could obviously shrink the peritoneal foci formed by gastric cancer cells which HOXA11 was induced, there still remained foci in the abdomen of mice." (PMID 31695791, 2019). "The adhesion assay was performed to test whether the affinity of gastric cancer cells for peritoneal mesothelium were affected by HOXA11, and significant differences were detected." (PMID 31695791, 2019). "Taken together, the adhesion and stemness ability of gastric cancer cells might be achieved through the HOXA11-Stat3-CD44s signaling axis described here." (PMID 31695791, 2019). "Furthermore, the IC50 of the inhibitory activity of BBI608 in gastric cancer cells which HOXA11 was induced (NCI-N87-HOXA11: 3.0 μM; SGC-7901-HOXA11: 6.5 μM) were higher than their control ones (NCI-N87-Vector: 0.4 μM; SGC-7901-Vector: 2.8 μM)." (PMID 31695791, 2019). "Furthermore, compared with the equivalent control concentration of DMSO, BBI608 rescued the apoptosis level of gastric cancer cells which was downregulated by HOXA11 (NCI-N87: P<0.0001; SGC-7901: P<0.0001)." (PMID 31695791, 2019).
gastric cancer (continued). "To determine whether HOXA11 could enhance the peritoneal metastatic ability of gastric cancer cells, we engineered NCI-N87 cell to overexpress HOXA11, and injected them intraperitoneally into BALB/c mice, along with empty vector controls." (PMID 31695791, 2019). "Finally, HOXA11 is known to promote gastric cancer and renal cancer." (PMID 37834206, 2023). "HOXA11 had the ability to change the stemness property of gastric cancer cells via forming a novel positive feedback loop with Stat3, and through such reprogramming, to modulate the adhesion, migration/invasion and anti-apoptosis phenotype of gastric cancer cells." (PMID 31695791, 2019). "Previous study shows that HOXA11 might inhibit gastric cancer through Wnt signaling pathway." (PMID 28038461, 2017). "Nonetheless, epigenetic changes and the effect of HOXA11 on gastric cancer remain unclear." (PMID 25788862, 2014). "The mRNA expression of HOXA11 was positively correlated with the expression level of CD133 (R=0.13, P=0.014) and Bmi1 (R=0.16, P=0.0023) in gastric cancer tissues of TCGA database." (PMID 31695791, 2019). "Moreover, CK636, the small molecule inhibitor of Arp2/3 complex which has been confirmed to participate in the process by which HOXA11 regulates the migration and invasion of gastric cancer cells, could also downregulate the expression of Arpc2 and Arpc3 which were upregulated by HOXA11." (PMID 31695791, 2019). "Immunofluorescence analysis confirmed that mesenchymal marker (N-cadherin) were upregulated in gastric cancer cells which HOXA11 was induced, by contrast, N-cadherin was downregulated in MGC-803 cell which HOXA11 was knocked-down." (PMID 31695791, 2019). "The methylation level of HOXA11 gene in gastric cancer tissues and adjacent non-cancerous tissues were higher than those in normal gastric mucosa (P < 0.05)." (PMID 25788862, 2014). "HOXA11 was selected for further investigation since it fulfilled all the other criteria which have been chosen, such as: 1) The GEO database and TCGA database have shown that expression of HOXA11 is higher in gastric cancer rather than gastric tissue." (PMID 31695791, 2019). "Correspondingly, downregulation of HOXA11 in MGC-803 parental cells reduced adhesion to HPMC to the levels shown by parental shControl cells (MGC803: #1: P<0.001 and #2: P<0.0001), confirming that HOXA11 promote gastric cancer cells to adhere to the peritoneal mesothelium." (PMID 31695791, 2019).
lung carcinoma (9 papers, 2011 to 2021). "However, overexpression of HOXA11 showed a poor association with overall survival in lung cancer." (PMID 32296636, 2020). "MIR196A1 and HOXA11 have been reported to be highly methylated in the bronchial washings of lung cancer patients." (PMID 34620221, 2021). "Evidence has demonstrated that homeobox (HOX) A1 (HOXA1) and HOXA11 play oncogenic roles in lung cancer, and they are the putative target genes of miR-181c-3p, as same as ZIC2, as analyzed by the bioinformatics analysis using the starBase database." (PMID 34232917, 2021). "In the further study, we intend to elucidate the exact regulatory mechanism and probably signaling pathways involved of the HOXA11 gene in human lung cancer." (PMID 28380439, 2017). "We chose eight human lung cancer cell lines from our cell bank to detect HOXA11 protein expression by a western blot estimation of the HOXA11 protein band intensity normalized to Tubulin." (PMID 28380439, 2017). "HOXA11 hypermethylation has been reported in lung cancer, but its functional relationship with malignant phenotype in lung cancer has remained elusive." (PMID 24259349, 2013). "Transient transfection of HOXA11 into H23 lung cancer cells resulted in the inhibition of cell migration and proliferation." (PMID 24259349, 2013). "Nonetheless, the clinicopathological significance of its methylation remains to be uncovered for lung cancer, and HOXA11 hypermethylation is currently a target of active research." (PMID 24259349, 2013). "HOXA11 hypermethylation was characterized in six lung cancer cell lines, and its clinical significance was analyzed using formalin-fixed paraffin-embedded tissues from 317 NSCLC patients, and Ki-67 expression was analyzed using immunohistochemistry." (PMID 24259349, 2013). "Second, The effect of HOXA11 on cell migration and proliferation was performed in only H23 lung cancer cells." (PMID 24259349, 2013). "HOXA1 and HOXA11 have been identified to play oncogenic roles in lung cancer." (PMID 34232917, 2021). "Therefore, we hypothesized that the HOXA11 gene could be regulated by the formation of a loop between Wnt5a and Wnt7a in human lung cancer." (PMID 28380439, 2017). "For example, P16, HOXA11 (Homeobox A11) and SOX17 (SRY-box 17) showed abnormal hypermethylation at their promoters, they were considered as biomarkers for lung cancer detection and prognosis prediction." (PMID 29169318, 2017). "To estimate the clinical significance of HOXA11, we investigated the HOXA11 protein expression in TMA from 160 lung cancer patients by using immunohistochemical analysis." (PMID 28380439, 2017). "These three co-expressed genes and HOXA11 might play several pivotal roles in LUSC, such as the subtype differentiation of lung cancer, the regulation of LUSC progression, and the development of efficient therapeutic strategies." (PMID 29914539, 2018). "The promoter region of HOXA11 was highly methylated in six lung cancer cell lines, but not in normal bronchial epithelial cells." (PMID 24259349, 2013).